INS (insulin)
Diseases named in the same sentence as INS in open-access papers (continued):
Sharing a sentence is not in itself a finding about the gene and the disease.
Hypertension (continued). "In this cross-sectional study based on a Japanese normoglycemic population, we explored the association of TyG, a surrogate indicator of non-insulin-based IR, with hypertension and prehypertension." (PMID 37964964, 2023). "In vitro studies revealed that incubation of the finger vessels in high concentrations of insulin results in the loss of their ability to expand and vessel hypertension in insulin-resistant horses." (PMID 37628596, 2023). "These cardiac changes are suggested to be linked with high blood pressure and decreased insulin sensitivity." (PMID 37507421, 2023). "Obesity is also associated with elevated aldosterone and insulin levels, both of which stimulates ENaC to conserve sodium and are thought to be a likely cause of refractory hypertension in this population." (PMID 36093171, 2022). "Current treatment strategies of DCM still focus on improving glycemic control and enhancing insulin sensitivity, as well as other adjunctive treatments targeting risk factors such as hypertension and hyperlipidemia." (PMID 36405687, 2022). "Fat forms artery plaque, which narrows arteries and capillaries leading to hypertension (a component of MS) and decreasing insulin sensitivity, consequently leading to a greater risk of MS." (PMID 36580471, 2022). "Loss of sensitivity to insulin action contributes to hypertension due to the loss of the vasodilator effect of insulin and vasoconstriction caused by FFAs." (PMID 35455055, 2022). "Age, body mass index, smoking status, hypertension, and chronic kidney disease all are factors that can potentially distort the measure of the association between the use of home insulin and poorer outcome." (PMID 35725489, 2022). "NO is a cellular signaling molecule associated with insulin secretion and intestinal peristalsis; however, excessive NO production can lead to hypertension, stroke, and inflammatory responses." (PMID 35668352, 2022). "Studies have shown that insulin promotes the proliferation and migration of VSMCs, leading to vascular remodeling and neointima formation, subsequently causing hypertension and other cardiovascular diseases." (PMID 36479179, 2022). "In insulin-resistance settings, the development of hypertension is due to the loss of the vasodilator effect of insulin and the vasoconstriction caused by FFAs." (PMID 36364903, 2022). "There are well-established physiological benefits of weight loss for hypertension, such as improvement in insulin sensitivity and a decrease in sympathetic nervous system activity and inflammation." (PMID 36301618, 2022). "Hypertension is caused by the accumulation of visceral fat and/or increased body weight, as well as increased levels of insulin, blood glucose, visceral mass, and/or decreased HDL cholesterol." (PMID 35215391, 2022). "Hypertension tends to be associated with metabolic risk factors, and about half of hypertensive patients are insulin-resistant." (PMID 35329071, 2022). "VAI as a specific index of visceral adiposity disorders has been widely associated with cardiovascular diseases, hypertension, human purine metabolism, insulin resistance and thyroid function." (PMID 36531468, 2022). "High insulin levels can increase sodium retention in renal tubules which can causatively induce hypertension." (PMID 36536959, 2022). "DM duration, insulin treatment, HbA1c level, and microalbuminuria were major risk contributors in a Spanish study, while the presence of hypertension, DM family history, and low frequency of physical activity were risk factors in a Danish study." (PMID 35211344, 2022). "Systemic risk factors, such as hypertension, hyperlipidemia, and smoking at baseline, were similar between the intensive insulin and oral hypoglycemic agent groups." (PMID 35459162, 2022). "Duffey and Davy indicated that higher HBI scores were associated with a lower risk of hypertension and also lower levels of C-reactive protein, insulin, FBS, and cholesterol." (PMID 36660267, 2022).
Hypertension (continued). "A meta-analysis that included 11 studies reported a pooled adjusted relative risk of hypertension of 1.43 (95% CI 1.27–1.62) for homeostasis model assessment insulin resistance when comparing the highest and lowest categories." (PMID 36014784, 2022). "This is important for long-term cardiovascular risk, since elevated insulin levels accelerate accumulation of central obesity, hypertension and atherogenicity of lipids with consequent atherosclerosis." (PMID 34684423, 2021). "Univariate linear regression showed that age, body mass index, HbA1c, MHR, sex, smoking, hypertension, history of coronary artery disease, oral antidiabetic drugs and insulin had association with CAVI with p value < 0.25." (PMID 34330221, 2021). "Physical activity reduces the risk of hypertension by reducing body weight, reducing psychological stress, improving insulin sensitivity, and reducing sympathetic activity." (PMID 34844564, 2021). "Decreased insulin sensitivity leads to hyperinsulinemia as a compensatory mechanism, ultimately causing hypertension via activation of the renin angiotensin aldosterone system." (PMID 33716966, 2021). "Age, ethnicity, insulin therapy, presence of hypertension, and hyperlipidemia were significantly associated with left ventricular diastolic dysfunction." (PMID 34646868, 2021). "IR has been recognized as an independent risk factor of hypertension, and insulin mediated-activation of endothelial IRS-1/PI3K/AKT/eNOS pathway is unique biological action for regulating vasodilation and arterial pressure." (PMID 33841146, 2021). "Intriguing positive associations between diet quality and hypertension among older adults, postprandial glucose level among prediabetic individuals, and insulin treatment among diabetic patients were found." (PMID 33924050, 2021). "The glucose metabolism has been implicated in insulin release and insulin sensitivity, which consequently influences the progression of hypertension by an increase in sodium reabsorption, SNS, and calcium concentration in vascular smooth muscle cells (VSMC)." (PMID 34677402, 2021). "Adjusting for prevalent hypertension and dyslipidaemia and excluding participants treated with insulin, all representing risk factors for microvascular complications positively associated with BMI, did not change the association." (PMID 33452586, 2021). "Age, ethnicity, insulin therapy, and presence of hypertension and hyperlipidemia were significantly associated with LVDD in our study." (PMID 34646868, 2021). "Hypoxic exercise training has been shown to decrease arterial stiffness, metabolic risk factors like body fat and insulin resistance, which all have been implicated in the pathogenesis of hypertension." (PMID 33355713, 2021). "We examined the association between insulin signaling markers and history of hypertension (identified at any time point in the study)." (PMID 33858515, 2021). "From a recent review in J Hypertension, they stated that from “Our analysis suggests that insulin plays a primary role in hypertension, highlighting the tight link between essential hypertension and diseases associated with the metabolic syndrome”." (PMID 34434951, 2021). "Age, hypertension, BMI and plasma glucose at admission, peripheral oxygen saturation, micro- and macroangiopathy, and insulin treatment were independently associated with hospitalization risk (p < 0.05)." (PMID 33233575, 2020). "The Uox−/− mice were viable and fertile but had a high mortality of 65% at 4 weeks of age because of severe nephropathy and ~40% 5 weeks of age because of renal dysfunction, metabolic disorders associated with compromised insulin secretion, hypertension." (PMID 32707836, 2020). "FPG, PPG, and INS levels were associated with residence, hypertension, and BMI; furthermore, FPG and PPG levels increased with age group." (PMID 33014972, 2020).
Hypertension (continued). "Elevated insulin levels also increase the risk of hypertension by enhancing renal reabsorption of sodium ions by several transport systems in different segments of the nephron." (PMID 32819363, 2020). "Metformin (plus insulin when required) is associated with low incidence of pregnancy induced hypertension." (PMID 33403188, 2020). "There were significant differences between the two groups with respect to age, weight loss, habitual alcohol use, ASAPS grade, DM with insulin use, hypertension, serum albumin, serum creatine, clinical tumor depth (cT), and clinical lymph node metastasis (cN)." (PMID 31583502, 2020). "Multivariate regression analysis revealed plasma sLRP1 levels [odds ratio (OR) = 0.971, p = 0.005] and HbA1c (OR = 1.298, p = 0.003) as a risk factor for MCI in diabetic patients, in addition to insulin use and hypertension." (PMID 33013281, 2020). "The results indicated that in addition to insulin use and hypertension, HbA1c and plasma sLRP1 levels are associated with MCI in patients with T2DM." (PMID 33013281, 2020). "The associations between quartiles of changes in fasting insulin and IR indices with incident hypertension were assessed using multivariate Cox proportional hazard regression analyses with first quartile as reference." (PMID 31728151, 2019). "Insulin alone has long been thought to cause Na+ retention, with enough effects to contribute to arterial hypertension." (PMID 31766426, 2019). "In view of the beneficial effects of DPP-4i on blood pressure regulation, we aimed to review the effects of DPP-4i upon hypertension in association with the immune system, blood vessels, the nervous system, hormones, kidneys, and insulin resistance." (PMID 31134095, 2019). "Changes in fasting insulin and IR indices were significantly associated with developing hypertension among normotensive population even after considering BMI changes." (PMID 31728151, 2019). "Several previous studies have investigated the associations of insulin levels and IR indices, using snapshot values of these measures alone, with consequent hypertension." (PMID 31728151, 2019). "A meta-analysis from 10 prospective studies showed that compared to the lowest quartile of fasting insulin concentrations, the highest quartile was associated with a pooled relative risk (95% CI) of 1.63 (1.35–1.97) for hypertension." (PMID 31728151, 2019). "It is caused by deficiency or diminished effectiveness of endogenous insulin or the improper use of insulin by target cells, and is characterized by deranged metabolism, hypertension, and sequelae predominantly affecting the vasculature." (PMID 30805250, 2019). "At present, the generally accepted mechanisms underlying hypertension are said to involve nerves, kidneys, hormones, blood vessels, and insulin resistance." (PMID 31134095, 2019). "Changes in fasting insulin levels increased risk of incident hypertension among those with normal insulin at baseline in different models." (PMID 31728151, 2019). "We found that insulin-deficient diabetes was associated with significantly lower levels of renal dopamine and norepinephrine while hypertension was associated with significantly greater levels of these catecholamines." (PMID 31040788, 2019). "Camk2n1 knockout in SHR, ameliorated multiple pathophysiological phenotypes including hypertension, LV mass, insulin sensitivity, and visceral adiposity, associated with reduced cardiorenal CaMKII activity and independent of adipose CaMKII activity." (PMID 31327268, 2019). "It was also demonstrated that muscle insulin sensitivity is significantly associated with hypertension in non-obese subjects and that insulin sensitivity is a risk factor for hypertension." (PMID 29324821, 2018). "Salt avidity is higher in insulin resistant than in insulin deficient states, which plays an important role in the early onset of hypertension in T2DM15." (PMID 29391429, 2018).
Hypertension (continued). "In the present study, insulin sensitivity assessed by the ISIMatsuda, insulin treatment, hypertension and serum UA, was significantly associated with an increase in the QTc interval apart from non-modifiable risk factors including age and female." (PMID 28912840, 2017). "Risk factors such as hypertension, dyslipidaemia, insulin sensitivity are shared by both dementia and CVD." (PMID 29273039, 2017). "In this study, our major findings are as follows: First, high-fructose feeding caused systolic hypertension and increased serum glucose, insulin, triglycerides, and total cholesterol levels, consistent with the findings of other and our previous reports." (PMID 28700686, 2017). "Low insulin sensitivity and high blood pressure.Increased intra-abdominal fat and higher risk of metabolic complications.Increased arterial stiffness.Reduced ventricular size and volume; impaired systolic function." (PMID 28603716, 2017). "Whereas older age, female gender, hypertension, high insulin, and high uric acid were also found to be risk factors, a high dioxin level was an independent predictor of CKD after adjusting for the effects of those factors." (PMID 26963719, 2016). "Blood pressure is directly related to body mass index, and individuals withincreased waist circumference have higher risk of developing hypertension,insulin resistance, and other metabolic changes, since adolescence." (PMID 27007222, 2016). "This diet is associated with increased insulin sensitivity, and reduced risk of cardiovascular disease, hypertension, and cancer." (PMID 27649232, 2016). "Our study showed that uric acid was an independent risk factor of CKD after adjusting for gender, age, hypertension, and insulin level." (PMID 26963719, 2016). "The increasing level of fasting C-peptide was still significantly associated with an increased risk of CAD in this model, and insulin treatment, hypertension and hyperlipidemia were also shown to lead to a significantly increased risk." (PMID 26098780, 2015). "For instance, in HFD-fed mice, a FFA-mediated impairment of both basal and insulin-induced eNOS phosphorylation has been reported in peripheral vessels and associated with endothelial dysfunction and hypertension." (PMID 25093405, 2014). "Fructose-fed rats and mice show moderate hypertension and glucose intolerance, associated with increased levels of plasma insulin, cholesterol and triglycerides." (PMID 25495455, 2014). "In fact, the sum of risk factors (hypertension + ovariectomy + fructose overload) promoted an increase in body weight, adipose tissue and triglyceride concentration along with impaired insulin sensitivity in FHO rats." (PMID 25495455, 2014). "Even though the consensus has been that insulin resistance is correlated with hypertension, the association between insulin and hypertension is controversial." (PMID 22013516, 2012). "Intensive insulin treatment, although beneficial in decreasing the risk of diabetic complications, can result in weight gain and its consequences, such as hypertension and a more atherogenic lipid profile." (PMID 20716374, 2010). "We did not study the effects of FM gain on other aspects of risk factors for CVD, such as insulin sensitivity or hypertension." (PMID 20964833, 2010). "Individuals with elevated resting heart rate have been shown to have high cholesterol, triglycerides and fasting insulin which are known risk factors for hypertension." (PMID 16509988, 2006). "Potential mechanisms that may explain the association between muscle strength and hypertension involve insulin resistance and skeletal muscle mass loss." (PMID 41310547, 2025). "Moreover, age, male, BMI, SBP, hypertension, use of sulphonylurea, insulin and DPP4-i, and prior CVD or DR were associated with increased CKD risk whereas haemoglobin and statins use were associated with decreased CKD risk." (PMID 40098113, 2025).
Hypertension (continued). "Although the mechanisms linking mental health conditions are not fully understood, several biological processes such as adiposity, insulin resistance, vascular function and oxidative stress, and inflammation have been implicated in the association between mental health conditions and hypertension." (PMID 39994423, 2025). "In obese people, who are already at increased risk of hypertension due to factors such as increased sympathetic activity and insulin resistance, the additional vasoconstriction mediated by vasopressin may precipitate or aggravate hypertensive states." (PMID 40136609, 2025). "Additionally, earlier studies have shown that prolonged sedentary behavior is negatively associated with cardiometabolic risk factors, such as childhood obesity, hypertension, abnormal cholesterol levels, and elevated insulin." (PMID 41026693, 2025). "Furthermore, our findings suggest that T2D patients with hypertension and insulin exposure have a significantly lower risk of developing insomnia disorders compared to those treated with DPP4is and SUs." (PMID 40836299, 2025). "In contrast, chronic smoking may cause endothelial dysfunction, vascular injury, plaque progression, and increases in insulin resistance and arterial stiffness, which could be associated with the development of hypertension." (PMID 39516368, 2025). "The activity of NHA2 is linked to hypertension and insulin secretion." (PMID 40362458, 2025). "The increase in sympathetic activity is observed early with weight gain and, if prolonged, is associated with complications, including high blood pressure and structural and functional alteration in the heart, and detrimental changes in circulating lipids and insulin sensitivity." (PMID 40422864, 2025). "Furthermore, the study examines the intermediate roles of HbA1c, insulin, and hypertension in the associations between TyG and TyG-WHtR with these diseases." (PMID 39026233, 2024). "Additionally, the association between daily sodium intake and insulin dose with hypertension requires more detailed assessment." (PMID 38864872, 2024). "Recently, we showed that excess intracellular Ca2+, a known pathogenic factor in hypertension, acts as a critical negative regulator of insulin signaling by forming Ca2+-phosphoinositides that prevent the membrane localization of AKT, a key serine/threonine kinase signaling molecule." (PMID 37121975, 2023). "Previously, it has been shown that habitual short-term sleep as well as irregular sleep cycles are associated with circadian misalignments and may lead to an increased risk of hypertension or reduced insulin sensitivity." (PMID 37208462, 2023). "BC/A is associated with hypertension, and it not only could predict future cardiac events in patients with heart failure but may also influence insulin resistance during pubertal development in girls." (PMID 37176802, 2023). "The literature confirms that the lack of physical activity significantly increases the risk of hypertension, dyslipidaemia, and insulin insensitivity, which may affect the quality of life." (PMID 37663865, 2023). "Among them, urinary sodium, urinary potassium, the urinary sodium/creatinine ratio, serum calcium, eGFRcrea, eGFRcys, fasting insulin, and hypertension might increase the risk of kidney stones." (PMID 37810889, 2023). "Hypertension may be caused by insulin's stimulation of the sympathetic nervous system, increase in salt retention in the kidneys, modulation of cation transport, and induction of vascular smooth muscle hypertrophy." (PMID 37274075, 2023). "Our data showed that insulin treatment was associated with lower risk of uncontrolled hypertension." (PMID 34917355, 2022). "In contrast, both MAP and insulin sensitivity are independently associated with hypertension at follow-up when modelled together (OR 2.16, 95% CI 1.90–2.46, p<0.001 for MAP higher by 1 SD; OR 0.79, 95% CI 0.68–0.92, p=0.003 for insulin sensitivity higher by 1 SD)." (PMID 33536549, 2022).